PANX1 (pannexin 1)
Diseases named in the same sentence as PANX1 in open-access papers (continued):
Sharing a sentence is not in itself a finding about the gene and the disease.
Intellectual disability (5 papers, 2017 to 2024). "Of note, a recent study identified a human PANX1 variant with multi-organ developmental abnormalities associated with marked intellectual disability." (PMID 31118206, 2019). "The discovery of the first patient bearing a homozygous Pannexin 1 (Panx1) loss-of-function gene variant associated with multisystem dysfunction and intellectual disability has been recently published." (PMID 29375373, 2017). "A germline PANX1 SNP was associated with intellectual disability." (PMID 32737184, 2020). "Six clinically significant independent variants of the PANX1 gene lead to human infertility and oocyte development defects, and the Arg217His variant was associated with pronounced symptoms of primary ovarian failure, severe intellectual disability, sensorineural hearing loss, and kyphosis." (PMID 34067798, 2021).
liver fibrosis (5 papers, 2017 to 2025). "However, some studies have also shown that PANX1 deficiency protects mice from acute and chronic liver failure as well as chemically-induced liver fibrosis, likely due to a reduction in the release of pathological levels of ATP from apoptotic or injured hepatocytes." (PMID 38937853, 2024). "In bile ligation induced liver fibrosis, Panx1 mRNA expression level was increased and Panx1-KO mice exhibited exacerbated liver damage, increased oxidative stress and elevated numbers of macrophages recruitment." (PMID 40909173, 2025). "Thus, blocking Panx1 channels prevents the development of hepatic fibrosis in a murine model of TAA-induced fibrosis." (PMID 37492223, 2023). "Similar to NASH, enhanced hepatic Panx1 RNA expression is also seen during liver fibrosis in mice." (PMID 37492223, 2023). "However, it has been recently suggested that TDF blocks Pannexin-1, which results in decreased adenosine levels and hence diminishes adenosine a2 receptor (A2AR)-mediated skin and liver fibrosis." (PMID 34879114, 2021).
migraine headaches (5 papers, 2020 to 2024). "CSD triggers neuroinflammation via the pannexin-1 (Panx1) channel opening, which may eventually cause migraine headaches." (PMID 32070042, 2020). "Panx1 contributes to many physiological and pathological processes, such as migraine headaches, spinal cord injury, sciatic nerve injury, cancer pain, and inflammatory pain." (PMID 38685116, 2024). "Panx1 hemichannel blockers, including PBN, suppressed this inflammatory response and abolished the headaches, which further supports the relationship between Panx1 hemichannels and inflammation." (PMID 37371611, 2023). "Blocking Panx1 channels by TAT-Panx308 inhibited CSD-induced headache related behaviour and HMGB1 release." (PMID 37495957, 2023). "Growing evidence supports the role of pathological activity of Panx1 channels in migraine headache and mechanisms of central sensitization during persistent pain." (PMID 36613527, 2022). "Next, we studied whether the acute effects of CSD on headache-related behaviour and cortical HMGB1 release could be prevented by blockade of neuronal Panx1 channels, as these channels open within minutes following a CSD and mediate an inflammatory cascade as part of trigeminovascular activation." (PMID 37495957, 2023).
testicular cancer (5 papers, 2019 to 2025). A primary or metastatic malignant neoplasm that affects the testis. "In testicular cancer, inhibition Panx1 function hindered cell migration and invasion, and downregulated the expression of p-ERK1/2, vimentin and matrix metalloproteinase 9 (MMP9)." (PMID 40909173, 2025). "Carbenoxolone can also act as the inhibitor of Pannexin 1 (Panx-1) and suppress the migration and invasion of testicular cancer cells to counter cancer progression and metastasis." (PMID 34368124, 2021). "In some cases, such as testicular cancer PANX1 activity was required for ERK1/2 activity, E-cadherin and metalloproteinase 9 (MMP-9) revealing that these channels contribute with different aspects of cell migration." (PMID 34975840, 2021). "This scenario is supported by data from recent studies on testicular cancer cells, where PANX1 inhibition downregulates EMT genes, upregulates E-cadherin, downregulates MMP-9, and decreases cell invasion." (PMID 31817827, 2019). "Similar results have been recently reported in testicular cancer cells, where downregulation of PANX1 or its inhibition downregulated vimentin protein levels and upregulated E-cadherin protein levels, through signal-regulated kinase (ERK)." (PMID 31817827, 2019). "In conclusion, high Panx1 expression could sensitize patients with testicular cancer to chemotherapy drug DDP treatment." (PMID 40909173, 2025). "In addition, they also uncovered that in testicular cancer cells, overexpression of Panx1 was consistent with Mechanistic Target of Rapamycin (mTOR) phosphorylated and higher p62 levels, inhibiting autophagy caused by DDP resistance." (PMID 40909173, 2025). "Indeed, PANX1 promotes motility, transmigration, and in vivo invasion in melanoma, breast and testicular cancer cells: B16-BL6, B16-F10; CN34, CN-LM1A, MDA-MB-231 MDA-MB-468, MDA-LM2, and I-10 cells, respectively." (PMID 34975840, 2021).
Alzheimer disease (4 papers, 2012 to 2023). A progressive, neurodegenerative disease characterized by loss of function and death of nerve cells in several areas of the brain leading to loss of cognitive function such as memory and language. "Dysregulation in these same cellular processes are observed in ASD, schizophrenia, Parkinson’s disease, and Alzheimer’s disease, and PANX1 has been linked to these conditions." (PMID 37807670, 2023). "Supporting this, recent work suggests that spine and synaptic plasticity deficits in a mouse model of Alzheimer’s disease can be mitigated by blocking PANX1." (PMID 37807670, 2023).
brain injuries (4 papers, 2018 to 2024). "Genetic deletion of myeloid Panx1 reduces tissue damage, blood–brain barrier leakage and improves behavioral outcomes after brain trauma." (PMID 32819386, 2020). "A major finding from our work is that myeloid Panx1 promotes acute infiltration of pro-inflammatory cells after brain trauma, which consequently impacts the neuroinflammatory response and outcomes after TBI." (PMID 32819386, 2020). "It is therefore possible that opening of Panx1 channels might potentiate the secondary damage response triggered by brain trauma." (PMID 29439712, 2018). "Our results coupled with our previous pharmacological findings support a model whereby blockade of Panx1 channels improves outcome after TBI and further strengthens the potential for cell-specific Panx1 targeted strategies to treat brain injuries." (PMID 32819386, 2020). "Our results indicate that genetic deletion of myeloid Panx1 reduced infiltration of peripheral leukocytes including inflammatory monocytes and neutrophils, decreased post-TBI memory and locomotor dysfunction, and ameliorated tissue damage and blood–brain barrier dysfunction after brain trauma." (PMID 32819386, 2020).
cerebral infarction (4 papers, 2020 to 2024). An ischemic condition of the brain, producing a persistent focal neurological deficit in the area of distribution of the cerebral arteries. "Interestingly, global PANX1 KO in mice protects against cerebral infarction in ischaemia, and this is at least partially mediated by endothelial (but not mural cell) PANX1 KO reducing contractile tone and attenuating leukocyte infiltration." (PMID 35581998, 2022).
depression (4 papers, 2018 to 2024). "Adjusted for sex, age and depression, neurotensin was negatively associated with MoCA score (r=−0.257, p=0.044), pannexin-1 was positively associated with the mean erroneous distance in the BVAT (r=0.270, p=0.033)." (PMID 38803679, 2024).
diabetes (4 papers, 2018 to 2026). "Therefore, the aim of this study was to compare Panx1 expression patterns during normal kidney development, in the normal postnatal kidney, and in the kidneys of patients with diabetes mellitus, a major cause of CKD." (PMID 35625681, 2022). "In the present work, it was demonstrated that diabetes-induced skeletal muscle atrophy is directly associated with enhanced sarcolemma permeabilization by non-selective membrane channels, and this effect was prevented by boldine, which is an inhibitor of Cx and Panx1 HCs as well as P2X7 receptors." (PMID 37189454, 2023). "The expression and activation of Cx43 and the expression of PANX1 are altered in distinct populations of renal cells during long-term type 2 diabetes mellitus, especially cells of the vascular wall." (PMID 41828379, 2026). "Since we found that distal tubule cells were most severely damaged in the same diabetes model, we concluded that Panx1 might play a role in distal tubule damage during diabetes." (PMID 35625681, 2022). "In our recent study of streptozotocin-induced diabetes mellitus in rats, we found almost exclusive expression of Panx1 in distal tubular cells from diabetic rats but not in those without diabetes." (PMID 35625681, 2022). "In addition, the glomerular and tubular expression of Panx1 was examined in patients with type 2 diabetes mellitus (DM2) and the control group, and renal Panx1 expression was correlated with serum creatinine." (PMID 35625681, 2022).
female infertility (4 papers, 2021 to 2025). Diminished or absent ability of a female to achieve conception. "Human germline PANX1 mutations which cause decreased protein abundance and trafficking defects lead to human oocyte death and female infertility." (PMID 33937260, 2021). "Recently, four independent families were reported in which different heterozygous PANX1 variants cause female infertility due to primary oocyte death." (PMID 33937260, 2021). "Homozygous variants in PANX1 have been found to cause oocyte death and female infertility." (PMID 39943208, 2025). "In this study, we designed a target-sequencing panel with 22 female infertility-related genes, namely, TUBB8, PATL2, WEE2, and PANX1 and sequenced 68 primary infertility (PI) and recurrent pregnancy loss (RPL) patients." (PMID 35620457, 2022).
gastric cancer (4 papers, 2016 to 2025). A primary or metastatic malignant neoplasm involving the stomach. "The impact of Panx1 also extends to gastric cancer, where its overexpression facilitates epithelial-mesenchymal transition (EMT) through the regulation of aquaporin 5 (AQP5), a critical mediator of signaling pathways involved in cell migration and invasion." (PMID 40978734, 2025). "In vitro models using gastric cancer cell lines revealed that AQP5 inhibition reverses the pro-migratory and invasive effects mediated by Panx1, further establishing the functional connection between these molecules in gastric cancer progression." (PMID 40978734, 2025).
injury (4 papers, 2017 to 2023). Damage inflicted on the body as the direct or indirect result of an external force, with or without disruption of structural continuity. "This indicates that the deletion of myeloid Panx1 improves the retention of spatial memory following brain injury." (PMID 32819386, 2020). "Thus, it is possible to hypothesize that Panx1 channel activation after brain trauma enhances the neuroinflammatory responses via ATP release." (PMID 29439712, 2018).
lung adenocarcinoma (4 papers, 2022 to 2024). A carcinoma that arises from the lung and is characterized by the presence of malignant glandular epithelial cells. "PANX1, a crucial gene closely associated with lung adenocarcinoma, was identified using the weighted correlation network analysis (WGCNA), and experiments revealed that PANX1 promotes the proliferation as well as invasion of LUAD cells." (PMID 38254708, 2024). "Many kinds of tumors are linked to abnormally high levels of PANX1 expression, including breast and skin tumors, but its study in lung adenocarcinoma is rare and deserves further investigation." (PMID 38254708, 2024). "The established ferroptosis-related gene signature associates the overexpression of PANX1 with unfavorable impacts on lung adenocarcinoma prognosis." (PMID 37492223, 2023). "Similar to IL-6, Panx1 mRNA was strongly expressed in poorly differentiated lung adenocarcinomas but was only weakly expressed in their well differentiated counterparts." (PMID 37696858, 2023). "A gene signature study on lung adenocarcinoma also identified the PANX1 gene as a ferroptosis-related prognosis gene." (PMID 37492223, 2023). "These experimental results indicated that PANX1 was a key molecule for tumor growth and metastasis, which may contribute to a worse prognosis for patients with lung adenocarcinoma." (PMID 38254708, 2024).
lung carcinoma (4 papers, 2021 to 2024). "Moreover, lung cancer patients with high expressions of IL-6, Panx1, or both IL-6 and Panx1 genes were associated with poorer overall survival than those having low expression levels of IL-6, Panx1, or both IL-6 and Panx1, respectively." (PMID 37385076, 2023). "The 8 FRGs (ACSL3, FADS2, GLS2, HSF1, PANX1, PHKG2, VDAC2, and CDKN1A) that we selected to be associated with the diagnosis and prognosis of lung cancer have been shown to play important roles in cancer and tumor immunity." (PMID 38743344, 2024). "Analysis of patient survival and relevant factors in lung cancer and pan-cancer cohorts supports the prognostic and clinical values of Panx1 and IL-6." (PMID 37696858, 2023). "Elevated Panx1 expression was correlated with impaired DFS and OS in lung cancer patients." (PMID 37696858, 2023).
multiple sclerosis (4 papers, 2013 to 2023). A progressive autoimmune disorder affecting the central nervous system resulting in demyelination. "Opening of Panx1 channels is implicated in a wide array of pathologies, including airway inflammation, autoimmune encephalomyelitis, brain trauma injury, joint pain, liver disease and multiple sclerosis." (PMID 37821897, 2023). "This secretion of ATP and UTP is governed by pannexin 1 (PANX1), a plasma transmembrane protein, and defects in this protein can result in multiple sclerosis and experimental allergic encephalomyelitis." (PMID 34926460, 2021). "We tested the hypothesis that Panx1-mediated ATP release contributes to expression of Experimental Autoimmune Encephalomyelitis (EAE), an animal model for multiple sclerosis, using wild-type (WT) and Panx1 knockout (KO) mice." (PMID 23885286, 2013). "Our data suggest that a Panx1-mediated pathway (ATP release and/or inflammasome activation) contributes to neuroinflammatory damage in the diseased spinal cord, and open the possibility that modulation of Panx1 could be a novel therapeutic target in multiple sclerosis." (PMID 23885286, 2013).
non-alcoholic steatohepatitis (4 papers, 2020 to 2024). "Previous studies have also reported that PANX1 mRNA was increased in the livers of mice with non-alcoholic steatohepatitis and various other liver diseases." (PMID 38937853, 2024). "PANX1 channels release ATP during lipoaptosis leading to c-Jun NH2-terminal kinase (JNK) activation in liver cells, revealing that hepatocytic PANX1 is key regulator of immune recruitment during nonalcoholic steatohepatitis (NASH) progression." (PMID 34975840, 2021). "Nevertheless, no alteration in the expression of pannexin 1 (Panx1, recently related to inflammation in non-alcoholic steatohepatitis and to liver damage) or the fibrosis markers transforming growth factor β1 (Tgfb1) or desmin (Des) was observed." (PMID 33374541, 2020).
pancreatic adenocarcinoma (4 papers, 2021 to 2025). "The high expression of PANX1 was associated with poor prognosis in multiple tumors, especially in pancreatic adenocarcinoma (PAAD)." (PMID 34796785, 2021). "The overexpression of Panx1 has been correlated with poor prognosis in multiple cancers, especially in pancreatic adenocarcinoma (PAAD), and immune infiltration of macrophages, neutrophils, and fibroblasts." (PMID 40227837, 2025). "High expression of PANX1 was significantly related to the poor outcome of multiple cancers, especially in pancreatic adenocarcinoma (PAAD)." (PMID 36601599, 2022).
skin cancer (4 papers, 2016 to 2025). "While the details of interactions between Panx1, Panx3, and inflammation in skin remain to be elucidated, these data provide support for the proposal that alterations in Panx3 levels and/or signaling contribute to skin tumor susceptibility through effects on acute inflammatory responses." (PMID 27506198, 2016).
squamous cell carcinoma (4 papers, 2014 to 2024). A carcinoma arising from squamous epithelial cells. "In our study, the expression of Cx37, Cx40, and Panx1 was investigated for the first time in surgically removed squamous cell carcinoma of the larynx by immunofluorescence method." (PMID 36833374, 2023). "Panx1 and Panx3 expression is lower in keratinocyte-derived basal cell carcinoma and squamous cell carcinoma, and a correlation has been reported between the aggressiveness of three isogenic metastatic melanoma cell lines and the level of Panx1 expression." (PMID 24600404, 2014). "Reduced levels of PANX1 and PANX3 in basal cell and squamous cell carcinomas compared to normal epidermal tissue supports the idea that the role of PANX1 may also differ between cancer subtypes." (PMID 30654593, 2019).
subarachnoid hemorrhage (4 papers, 2021 to 2024). A serious neurological disorder characterized by intracranial hemorrhage into the subarachnoid space. "In a rat model of subarachnoid hemorrhage, elevated expression of Panx1 channels exacerbated the inflammatory injury associated with TLR2/TLR4/NF-κB signaling." (PMID 35325354, 2022). "Indeed, headache is more prevalent after intracerebral hemorrhages and subarachnoid hemorrhage, which also activate Panx1 and downstream pathways." (PMID 34794382, 2021).
abdominal aortic aneurysm (3 papers, 2022 to 2024). Enlargement and ballooning of the vessel that supplies arterial blood to the abdomen, pelvis and legs. "Pannexin-1 channels on endothelial cells modulate ATP secretion to regulate the pathogenesis of abdominal aortic aneurysm formation." (PMID 39075542, 2024). "Recently, Panx1 channels were identified to be significantly involved in abdominal aortic aneurysm formation through endothelial derived Panx1 regulated inflammation and aortic remodeling." (PMID 36950521, 2023). "Since platelets play a role in cardiovascular diseases including abdominal aortic aneurysm, we analyzed the contribution of platelet Panx1 in the progression of abdominal aortic aneurysm." (PMID 36950521, 2023). "We detected enhanced Panx1 plasma levels in abdominal aortic aneurysm patients." (PMID 36950521, 2023). "Pannexin-1 (Panx1) channels have been shown to regulate leukocyte trafficking and tissue inflammation but the mechanism of Panx1 in chronic vascular diseases like abdominal aortic aneurysms (AAA) is unknown." (PMID 35315432, 2022). "Thus, aortic diameter expansion at different time points after elastase infusion of the aortic wall was unaltered in platelet-specific Panx1 deficient mice suggesting that the modulation of inflammation alone does not affect abdominal aortic aneurysm formation and progression." (PMID 36950521, 2023). "In experimental abdominal aortic aneurysm using the pancreatic porcine elastase (PPE) mouse model, a major contribution of platelet Panx1 channels in platelet activation, pro-coagulant activity of platelets and platelet-mediated inflammation has been detected." (PMID 36950521, 2023).
acute kidney injury (3 papers, 2022 to 2024). Sudden and sustained deterioration of the kidney function characterized by decreased glomerular filtration rate, increased serum creatinine or oliguria. "PANX-1 mediates necrosis-induced NLRP3 inflammasome activation in macrophages during acute kidney injury." (PMID 39075542, 2024). "Indeed, another study shows that danger signals from necrotic tubular epithelial cells could activate the NOD-like receptor protein 3 (NLRP3) inflammasome in macrophages through the TLR2/caspase 5/Panx1 axis during acute kidney injury (AKI)." (PMID 36555574, 2022).